TLR9 (toll like receptor 9)
Diseases named in the same sentence as TLR9 in open-access papers (continued):
Sharing a sentence is not in itself a finding about the gene and the disease.
tumor (continued). "TLR9 activation is similar to TLR3/ TLR7/TLR8 activation and results in increased expression levels of costimulatory molecules such as TRAIL, which can induce tumor cell death, and CCR7, which promotes trafficking of APCs to lymph nodes." (PMID 37112730, 2023). "Although TLR9 is widely expressed in all subsets of DCs but it is predominantly expressed by plasmacytoid DC (pDC) subset, so we further studied the effect of MIP on tumor infiltrating pDCs (Ti-pDC)." (PMID 37122749, 2023). "In a B16F10 subcutaneous tumor model, OX40 expression was significantly increased, with nearly 2-fold upregulation, on infiltrating CD4+ T cells after intratumoral injection of CpG, a ligand for TLR9." (PMID 37700338, 2023). "In contrast to the spleen, in tumor tissues, the combined effects of STING and TLR9 agonists resulted in an approximately 70-fold increase in IFN-β expression compared with the control group, which is a remarkable finding and indicates the pro-inflammatory status in the TME." (PMID 37901237, 2023). "The expression levels of TLR9 in monocyte-derived peritoneal macrophages decreased at week 3 after MC38 tumor inoculation, regardless of treatment." (PMID 36278484, 2022). "The activation of TLR9 on DCs and plasmacytoid DCs promotes the secretion of a large amount of type I IFN, which has both direct (tumor cell inhibitory effect) and indirect (antitumor immune responses) effects on cancer cells and is most evident in the early stages of antitumor immune responses." (PMID 35937402, 2022). "In addition to inhibiting autophagy, TLR9 and/or HGFR signaling pathways, the use of modified tumor self-DNAs allows the development of novel anticancer therapies." (PMID 35551547, 2022). "Here, we found that PRMs barely expressed TLR9 at baseline and after peritoneal tumor inoculation, as opposed to monocyte-derived macrophages." (PMID 36278484, 2022). "By administering an in situ injection of three drugs in combination, namely the TLR9 agonist CpG, agonistic anti-OX40 antibody and STING agonist cGAMP, we not only significantly slowed the growth of tumours at the injection site but also altered the growth of distant tumours." (PMID 34731284, 2022). "In humans, TLR9 is expressed only on the endosomal membrane of B cells and pDC and induces the recruitment of immune effector cells by activating an inflammatory-like innate response and inhibits the abundant presence of MDSC around the tumor mass." (PMID 36365103, 2022). "Tumor cells can release HMGB1 into the local microenvironment, where HMGB1 interacts with several receptors, such as toll-like receptor 2 (TLR-2), TLR-4, TLR-9, and the receptor for advanced glycation end products (RAGE), which can lead to tumor cell survival, proliferation, and angiogenesis." (PMID 34617194, 2022). "RT significantly enhanced the abundance of tumor-infiltrating CD317+CD11c+ pDCs and the injection of PIC into the radiated tumors increased the percentage of CD80+ cells, one of the markers of TLR-9 activation, among pDCs, when compared to the untreated control group 36,43." (PMID 35999216, 2022). "In vivo studies demonstrated that XL-MSNs co-delivered antigen peptide and TLR9 agonists could effectively target draining lymph nodes, induce tumor infiltration of antigen-specific cytotoxic T lymphocytes (CTL), and inhibit tumor growth." (PMID 35748543, 2022). "SD-101; an intratumoral toll-like receptor 9 (TLR9) agonist, is a novel immune priming strategy that was shown to modify the TME by increasing local production of type 1 Interferon, resulting in cytotoxic T-cell infiltration and an anti-tumor response." (PMID 36351947, 2022). "The discovery that hypoxic FaDu CM induced a significant iNOS2 expression in MΦ while FaDuTLR9def CM failed to do so is intriguing and indicates that tumor-based TLR9 can influence MΦ function in a specialized way." (PMID 34479492, 2021).
tumor (continued). "Immunostimulatory DAMPs include a release of endoplasmatic reticulum proteins like calreticulin and heat shock proteins (HSP), the toll-like receptor (TLR) 4 and TLR9 agonist high mobility group box 1 (HMGB1) and ATP, leading to DC recruitment and activation at the site of tumor cell death." (PMID 34025657, 2021). "In addition to silencing Wnt2b or β-catenin expression, TLR9 agonist CpG ODN downregulated the level of glycolysis and inhibited the M2 polarization of HCC-TAMs, reversing the tumour-promoting effects of TAMs in vitro and vivo." (PMID 33407720, 2021). "Moreover, we compared our findings with our previous work in which an antigen, a toll-like receptor 9 (TLR-9), and a chemotherapeutic agent were administered in combinations to a murine hot tumor model." (PMID 34680196, 2021). "We performed a comprehensive analysis of tumor-infiltrating immune cells in a cohort of intrahepatic and extrahepatic BTC, including innate immunity members such as TLR7, TLR9, and adaptive immunity factors such as CD4 and CD8 as well as PD-1 and PD-L1 expression at protein level." (PMID 34573939, 2021). "TLR9 overexpression increased HCC cell proliferation, whereas TLR9 inhibition from hydroxychloroquine (HCQ) decreased HCC cell proliferation, tumor growth, oxidative stress marker (SOD1), and the formation of autophagosome bodies (reduced ATG5 and Beclin-1 expression)." (PMID 34203465, 2021). "SLC15A4 is required for Toll-like receptor 7 (TLR7)- and TLR9-mediated type I interferon (IFN-I) production in plasmacytoid dendritic cells (pDCs) by the mTOR pathway, highlighting its role in regulating the immune response in the tumor microenvironment." (PMID 34168674, 2021). "Regarding the mechanism, we found TLR9 signaling and STAT3 activation in tumor cells." (PMID 32483468, 2020). "Also, tumors are able to downregulate TLR-9 on pDCs, indicating that although pDCs infiltrate the TME, their ability to elicit an anti-tumor response is diminished." (PMID 32602047, 2020). "Such a mechanism of tumor growth was also operative during exposure of cancer cell lines (Hepa 1–6, Huh 7) to hypoxia in vitro, and was attenuated by knockdown of either HMGB1 or TLR9." (PMID 32664328, 2020). "Tumor sphere formation was attenuated significantly by the TLR9 siRNAs compared with the negative control." (PMID 32843056, 2020). "Our findings provided evidence for the first time that OCT4-3 + TLR9 induced significantly stronger immune responses and suppressed tumor growth in BABL/c mice without any significant systemic toxicity." (PMID 32296581, 2020). "However, in combination with CpG ODN (cytosine guanine dinucleotide oligodeoxynucleotides, TLR9 agonist), MF59 has proven to induce effective anti-tumor responses in several murine cancer models." (PMID 33679703, 2020). "The induction of TLRs, especially TLR9, in tumor cells by endogenous ligands does not result in antitumor immunity but rather contributes to tumor progression 18-27." (PMID 32483468, 2020). "Similarly, approximately 55.17% of the tumor samples with high TLR9 expression showed strong p-STAT3 (Tyr705) staining, and 75.61% of those with low TLR9 expression showed weak p-STAT3 (Tyr705) staining (p < 0.001)." (PMID 32483468, 2020). "In stark contrast, this pattern was absent (Myd88, Cd4, Tlr9, Ly96) in tumor-bearing and/or –resected mice or reversed, in one case (C3)." (PMID 31019214, 2019). "The right flank tumor was then injected with 30μg of the TLR9 agonist ODN1826 or PBS on days 3, 6 and 9 with or without concordant injection of 100μg of the CTLA-4 blocking antibody 9H10 systemically." (PMID 31771649, 2019). "In addition to TLR9-mediated tumor DNA sensing, we have previously found that TLR4 also promotes activation of tumor-specific CTLs after chemotherapy by recognizing the chromatin-associated factor HMGB1 released from dying tumor cells." (PMID 31619293, 2019).
tumor (continued). "Moreover, to understand the influence of TLR4 and TLR9 haplotypes on tumor progression, we correlated the haplotypes with early (I and II) and late (III and IV) tumor stages." (PMID 31278284, 2019). "The transcriptomic analysis also showed that the relative expression of TLR9 mRNA was inversely correlated with the tumor size at diagnosis (p = 0.014; r = −0.314) but not with clinical stage (p = 0.117; r = −0.177)." (PMID 31886298, 2019). "Moreover, TLR9 agonists were also able to enhance radiofrequency-induced CTL responses, potentiating the inhibition of primary tumor growth and lung metastasis." (PMID 31547627, 2019). "The right flank tumor was then injected with 30μg of the TLR9 agonist MGN1703 or PBS on days 3, 6 and 9 with or without concordant injection of 100μg of the CTLA-4 antibody 9D9-mIgG2a systemically." (PMID 31771649, 2019). "Combined chemotherapy and vaccination led to persistent control of tumor growth in wildtype mice but not in their TLR9−/− counterparts." (PMID 31619293, 2019). "In contrast, there was no therapeutic benefit to systemic TLR9 agonist alone or in combination with checkpoint blockade likely reflecting a lack of specific immune activation in the tumor microenvironment." (PMID 31771649, 2019). "Particularly, we showed that TLR9 promotes the maturation and migration of antigen-presenting DCs from the TME to the regional lymph nodes, where they subsequently activate tumor-specific CTLs leading to effective tumor control." (PMID 31619293, 2019). "In our whole population-based study, we retrieved 150 Finnish NPC cases and studied their tumour samples for TLR1, TLR2, TLR4, TLR5, TLR7, and TLR9 expressions by immunohistochemistry, and for the presence of EBV and high-risk HPVs with EBV RNA and HPV E6/E7 mRNA in situ hybridizations." (PMID 31238894, 2019). "Tumor cells can release HMGB1 into the local microenvironment, where HMGB1 binds with high affinity to several receptors, such as toll like receptor-2 (TLR-2), TLR-4, TLR-9 and advanced glycation end products (RAGE), which can lead to tumor cell survival, expansion and metastasis." (PMID 30526680, 2018). "The activation via TLR2, TLR4 and TLR9 enhances IFN-γ levels, driving chemotaxis of neutrophils, DCs, and macrophages to the inoculation site, where they internalize the bacilli and/or tumor antigens, and spread through the lymphatic vessels." (PMID 29755647, 2018). "After toll like receptor 9 (TLR9) mediated NF-κB activation and IL-10 receptor blocking antibody, the infiltrating macrophages and DCs (which migrated toward an adenoviral expression of CCL16 on the tumors) would induce initial tumor necrosis." (PMID 29315242, 2018). "Surprisingly, unlike among Caucasian TNBC patient population, high tumor TLR9 protein expression did not protect from relapses among AA TNBC patients." (PMID 28886076, 2017). "TLR3 and TLR9 agonists have been shown to enhance iNKT cell’s ability to mature DCs, whereas tumor cells are thought to shed NKG2D ligands in exosomes to block the receptor from recognizing the tumor cell." (PMID 29163518, 2017). "The target tumor cells were added to BMDMs activated by the following TLR agonists; TLR1/2 agonist Pam3, TLR2/6 agonist LTA, TLR3 agonist poly(I:C), TLR5 agonist flagellin, TLR7 agonist CL264, and TLR9 agonist CpG." (PMID 29123526, 2017). "When TLR9 expression is absent or down-regulated, the growth promotion is lost, resulting in the net effect of tumor inhibition." (PMID 27888633, 2016). "Several published studies showed that TLR9 signaling could induce the activation of JNK(mitogen-activated protein kinase 8) and p38 MAPK (mitogen-activated protein kinases) pathway to enhance tumor growth." (PMID 26087186, 2015). "Consistently with our earlier studies, we did not observe target gene silencing or any antitumor effects of CpG-STAT3siRNA in TLR9-negative tumor xenotransplants in immunodeficient mice." (PMID 26046794, 2015).
tumor (continued). "Replacement of the radiosensitive haematopoietic compartment with TLR-2/-4−/− or TLR-9−/− cells did not affect tumour formation, in contrast to the role of TLR-4 on haematopoietic and non-haematopoietic cells in chemically induced skin carcinogenesis." (PMID 25575023, 2015). "Following tumor DNA treatment of HDFα fibroblasts, we observed no overexpression of the elements of TLR9 pathway, chemokines, growth factors, apoptosis related genes, prostaglandines and receptors for prostaglandines." (PMID 26133168, 2015). "Our gene expression results are confirmed align with observations in recent publications that demonstrated that intact tumor DNA binds as a ligand to TLR9 but does not result in downstream activation of TLR9 pathway." (PMID 26133168, 2015). "The silencing of TLR9 in PC-TLR9LO cells resulted in ~200-fold reduction in the TPC frequency (second panel) which corresponded to the previously observed delayed PC-TLR9LO tumor engraftment (right)." (PMID 26046794, 2015). "The vaccine, ISCOM+TLR9+OVA antigen, was able to induce strong immunity against the tumor and induce effective memory responses, including a high percentage of CD8+IFNγ+ T cells after re-induction of the tumor." (PMID 26344621, 2014). "Analysis of tumor cells from sorted bone marrow mononuclear cells of MM patients showed high TLR2, TLR4 and TLR9 mRNA levels and these findings were consistent with the high protein expression of TLR4 and TLR9 when analyzed by flowcytometry." (PMID 25112836, 2014). "It is also possible that TLR9 expression changes tumor immunophenotype independent of treatment and this aspect also requires further investigation." (PMID 25101078, 2014). "This inhibition was not due to downregulation of TLR9 expression or to a blockade of CpG internalization by tumor cells." (PMID 23561041, 2013). "Chloroquine treatment did not inhibit tumor growth in either the control siRNA or TLR9 siRNA groups." (PMID 24273604, 2013). "Indeed, the anti-tumor activities of Imiquimod, a ligand for TLR7, and CpG DNA, a ligand for TLR9, have been demonstrated in several clinical trials." (PMID 24098333, 2013). "Thus, TLR9 agonist could improve the therapeutic ratio of RT by providing radioprotection of normal moucosal tissues, while increasing the tumoricidal effects of primary tumor RT and induction of systemic anti-tumoral immunity for eradication of systemic metastases." (PMID 22666458, 2012). "Finally, in a model of murine colorectal CT26 tumor, pretreatment with TLR9 agonist protected the mice from lethal RIGS, while improving the tumor suppression after whole abdominal RT." (PMID 22238604, 2012). "Tumor specimens from untreated and TLR9 agonist-treated animals exhibited very weak immunofluroscence, indicating no deposition of auto-antibodies in tumor tissue in situ." (PMID 22666458, 2012). "In AIR+TLR9 agonist treated group 50% of mice survived more than 30 days and showed significant tumor growth retardation compared to untreated non-irradiated control (p<0.0001) (n = 10)." (PMID 22238604, 2012). "As the relevance of TLR9 to the tumor formation is not known yet, further study is needed to clarify this issue." (PMID 22427965, 2012). "Furthermore, TLR9 agonist activated NKDCs by upregualting the expression of both CD80 and CD86, while RT increased the tumor infiltration of NKDCs." (PMID 22666458, 2012). "The hazard ratio (HR) of patients without TLR9-expressing tumours was 2.40 (95% CI 1.24-4.63, p = 0.009)." (PMID 21929816, 2011). "The RCC-specific survival was significantly longer for patients whose tumours did express cytoplasmic TLR9, as compared with patients whose tumours were negative for cytoplasmic TLR9 expression (p = 0.007)." (PMID 21929816, 2011). "We found that the activation of TLR4 and TLR9 prevented, but did not reverse, metastasis because the potency of this combination was neither sufficient to overcome the tumor cell-educated immune tolerance nor to induce efficacious autophagy in tumor cells." (PMID 21931823, 2011).
tumor (continued). "Twenty-one (15%) of the tumours were strongly positive, 39 (28%) moderately positive, 52 (38%) weakly positive and 26 (19%) negative for cytoplasmic TLR9 immunostaining." (PMID 21929816, 2011). "Through binding on Toll-like receptor 9 (TLR9) the CpG ODNs induce an elevated expression of MHC I and II molecules as well as of co-stimulatory molecules on DCs which in turn acquire an increased ability to present tumor antigens to T and B effector cells." (PMID 20836870, 2010). "TLR9 expression by malignant tumor cells, would affect treatment approaches using CpG-ODN on the one hand, and, on the other hand, provide additional novel information about the role of tumor cells in tumor-immunology." (PMID 15631627, 2005). "The expression of functionally active TLR9 in human malignant tumors might affect treatment approaches using CpG-ODN and shows that malignant cells can be regarded as active players in tumor-immunology." (PMID 15631627, 2005). "Moreover, exDNA serves as a ligand for pattern recognition receptors (PRRs) such as Toll-like receptor 9 (TLR9), activating downstream signaling pathways that can support cancer progression by inducing pro-inflammatory cytokines and enhancing tumor-promoting inflammation." (PMID 40278350, 2025). "In terms of TLR ligand-targeted modulation of NK cells, TLR8 agonists (e.g., R848) and TLR9 agonists can respectively regulate immunomodulatory and cytotoxic NK cells, increase the expression of activation receptors such as NKG2D and NKp44, and synergistically enhance anti-tumor activity." (PMID 41488647, 2025). "Particularly, TLR9 was strongly expressed on human tumor cell lines of different tissue-origin, including lung cancer, gastric carcinoma, cervical tumor, and prostate cancer, suggesting that TLR-signaling might modulate tumor development." (PMID 39020402, 2024). "Therefore, we next used the CyTOF data to analyze TLR9-expressing antigen-presenting cells, as they could regulate the profound CD8+ T cell proliferation and trafficking into the tumor after CpG+RT." (PMID 39133651, 2024). "This is in the context whereby the tumor cells themselves do not respond to TLR9 signaling; therefore, combining such treatment with tumor profiling to identify TLR9 nonresponsive tumors would be beneficial to avoid any potential enhancement of a tumor’s invasive properties." (PMID 38201300, 2024). "In accordance, many TLRs agonists (imiquimod for TLR7 and CpG for TLR9) or cGAS-STING triggers were employed to activate anti-viral interferon-mediated immune responses with final aim to polarise myeloid cells towards an anti-tumour state, prime, and support T cell-mediated anti-tumour immunity." (PMID 36161514, 2023). "Toll-like receptor 9 (TLR9) expression by PCa cells, which appears central to tumorigenesis, stimulates recruitment of PMN-MDSCs via the proteins S100A8 and S100A9, and upregulates the transcription factor STAT3 which in turn inhibits CD8 T cell anti-tumor activity." (PMID 35603186, 2022). "In conclusion, our study indicates that TLR, and especially TLR9 ligation might be a mechanism by which infections can enhance a more efficient state of cancer immunosurveillance, even in the absence of tumor cells." (PMID 36714124, 2022). "CpG ODNs is a class of synthetic DNA fragments containing unmethylated cytosine phosphate guanine (CpG) dinucleotide, which could activate the innate immune system after binding with Toll-like receptor 9 (TLR9); therefore, it can be easily integrated with DNA hydrogels for tumor immunotherapy." (PMID 35877485, 2022). "Tumor growth inhibition was comparable between the WT and Tlr9−/− mice, demonstrating that host TLR9 may not be required for the antitumor effect induced by the irradiated vaccine." (PMID 32398808, 2021).